ENSG00000251478 (t-complex 1 (TCP1) pseudogene)
Synonyms: CCT1-2P; TCP1L2; TCP1P2
Gene: Processed pseudogene on chromosome 5 (41,585,882 to 41,587,787, reverse strand). Ensembl gene ENSG00000251478.
Diseases named in the same sentence as ENSG00000251478 in open-access papers:
ENSG00000251478 is named in the same sentence as 1 disease in open-access papers, as found by Europe PMC text mining. Sharing a sentence is not in itself a finding about the gene and the disease.
ENSG00000251478 shares sentences with these, for which no sentence is quoted: glioma (1 paper).